CDC123 (cell division cycle 123)
Description:
ATP-dependent protein-folding chaperone for the eIF2 complex. Binds to the gamma subunit of the eIF2 complex which allows the subunit to assemble with the alpha and beta subunits (By similarity).
Synonyms: C10orf7; D123
Tractability: Small molecule: a structure with a bound ligand is known. PROTAC: ubiquitination databases record sites on it; its protein half-life has been measured.
Gene: Protein-coding gene on chromosome 10 (12,195,950 to 12,250,595, forward strand). Ensembl gene ENSG00000151465.
Subcellular location: Cytoplasm
Subcellular location (Human Protein Atlas): Golgi apparatus; Nucleoplasm; Cytosol
Gene Ontology:
Molecular function: ATP binding; magnesium ion binding; protein binding; protein folding chaperone
Biological process: eukaryotic translation initiation factor 2 complex assembly; protein folding
Cellular component: cytoplasm
Genetic constraint (gnomAD): Loss-of-function variants: 28 observed, 37.89 expected, observed/expected ratio (o/e) 0.74, 90% interval 0.55 to 1.01. The upper end of that interval is the gene's LOEUF score, 1.01, which puts it in group 4 of 6, group 1 being the genes least tolerant of losing a copy. Missense variants: 281 observed, 320.6 expected, observed/expected ratio (o/e) 0.88, 90% interval 0.79 to 0.97. Synonymous variants: 113 observed, 105.69 expected, observed/expected ratio (o/e) 1.07, 90% interval 0.92 to 1.25.
Homologues: Orthologues: macaque CDC123 (99% identical), dog CDC123 (96% identical), guinea pig CDC123 (95% identical), rabbit CDC123 (95% identical), chimpanzee CDC123 (94% identical), pig CDC123 (93% identical), rat Cdc123 (93% identical), mouse Cdc123 (92% identical), zebrafish cdc123 (72% identical).
Diseases named in the same sentence as CDC123 in open-access papers:
CDC123 is named in the same sentence as 8 diseases in open-access papers, as found by Europe PMC text mining. Sharing a sentence is not in itself a finding about the gene and the disease. The quoted sentences say what the papers report.
type 2 diabetes (10 papers, 2008 to 2022). "A single nucleotide polymorphism (SNP) genotyping of 11,530 cases pointed out that SNP rs10906115A of CDC123/CAMK1D was significantly associated with susceptibility to type 2 diabetes in the Japanese population." (PMID 35910194, 2022). "In conclusion, we extend follow up studies of GWAS-identified type 2 diabetes-associated variants to the CDC123/CAMK1D locus on chromosome 10." (PMID 25211022, 2014). "Taken together, these data confirm that rs11257655 exhibits allelic differences in transcriptional enhancer activity and suggest it functions within a cis-regulatory element at the CDC123/CAMK1D type 2 diabetes-associated locus." (PMID 25211022, 2014). "In this study, we expand the lexicon of disease-associated functional regulatory variation by examining the type 2 diabetes-association signal at the CDC123/CAMK1D locus." (PMID 25211022, 2014). "Thus, our study provides strong evidence of a functional variant underlying the type 2 diabetes association signal at the CDC123/CAMK1D locus acting through altered regulation in type 2 diabetes-relevant cell types." (PMID 25211022, 2014). "We identified fourteen type 2 diabetes-associated genes discovered by the first waves of GWAS for which there was little prior evidence of their potential role in diabetes (Adam30, Adamts9, Camk1d, Cdc123, Cdkal1, Cdkn2a, Cdkn2b, Ext2, Hhex, Ide, Jazf1, Lgr5, Thada and Tspan8)." (PMID 23442068, 2013). "In humans, SNPs near the cell cycle genes CDC123 and CDKN2A have been found to be associated with increased susceptibility to type 2 diabetes." (PMID 29159468, 2018). "The CDC123/CAMK1D type 2 diabetes association signal on chromosome 10 spans an intergenic region between CDC123 and CAMK1D and also overlaps the CDC123 3′UTR." (PMID 25211022, 2014). "In cis-eQTL analyses, the rs11257655 type 2 diabetes risk allele was more strongly and directly associated with increased expression of CAMK1D than CDC123 in both blood and lung." (PMID 25211022, 2014). "A very recently published study investigated associations of the type 2 diabetes risk alleles in JAZF1, CDC123/CAMK1D, TSPAN8/LGR5, THADA, ADAMTS9, and NOTCH2 with obesity, insulin sensitivity, and insulin secretion in 4516 Danes." (PMID 18714373, 2008). "In the type 2 diabetes CDC123/CAMK1D GWAS (genome-wide association studies) locus, rs11257655 affects transcriptional activity by altering the binding of the protein complexes of FOXA1 and FOXA2, a potential molecular mechanism in type 2 diabetes." (PMID 35910194, 2022). "Our results from the blood glucose analysis validated well-established gene loci associated with type 2 diabetes with common SNPs in CDKAL1, SLC30A8, SND1-PAX4, IDE-KIF11-HHEX, CDKN2A-CDKN2B, KCNQ1 and CDC123,33,37,38 and identified a novel locus associated with FBG in DENND5B." (PMID 32355288, 2020). "The rs11257655-T allele associated with type 2 diabetes risk displayed increased enhancer activity relative to the C allele, suggesting that increased expression of one or more genes, possibly CAMK1D or CDC123, may be associated with type 2 diabetes." (PMID 25211022, 2014). "On BTA-13, CDC123 and CAMK1D genes have been reported to participate in various functions of pancreatic beta-cell and genetic variants at this locus have been associated to type 2 diabetes susceptibility in human." (PMID 24636660, 2014). "To determine whether CDC123 or CAMK1D are expressed in type 2 diabetes-relevant tissues, we measured and confirmed expression of both transcripts in human islets and hepatocytes." (PMID 25211022, 2014). "However, it is not unexpected that our study was unable to find significant associations between SNPs in JAZF1, CDC123/CAMK1D, TSPAN8/LGR5 and ADAMTS9 and type 2 diabetes, since the meta-analysis required more than 9000 samples for an 80% power." (PMID 20161779, 2010).
type 2 diabetes (continued). "Furthermore, a meta-analysis of three GWASs detected six novel variants (in JAZF1, CDC123/CAMK1D, TSPAN8/LGR5, THADA, ADAMTS9, and NOTCH2) that were associated with type 2 diabetes." (PMID 20161779, 2010).
Obesity (5 papers, 2008 to 2018). Accumulation of substantial excess body fat. "Five variants were top weighted (above the threshold of 0.75) in more than one cluster: CDC123/CAMKID (Beta Cell and Proinsulin), HSD17B12 (Beta Cell and Obesity), ADCY5 (Beta Cell and Lipodystrophy), CCND2 (Proinsulin and Lipodystrophy), and HNF4A (Beta Cell and Proinsulin)." (PMID 30240442, 2018).
diabetes (2 papers, 2013 to 2014). "While we confirm expression of CAMK1D and CDC123 in islets and hepatocytes, future studies over-expressing the target gene(s) in these tissues would be necessary to establish the mechanisms by which increased expression leads to diabetes risk." (PMID 25211022, 2014).
Insulin resistance (1 paper, 2014). Increased resistance towards insulin, that is, diminished effectiveness of insulin in reducing blood glucose levels. "In addition, T2D risk allele G of CDC123-rs12779790 was associated with a higher fasting insulin level (β (SE) = 0.03 (0.01), P = 8.58×10−3) and a greater HOMA-IR (β (SE) = 0.04 (0.01), P = 9.39×10−3), suggesting that this locus may be involved in insulin resistance." (PMID 24637646, 2014).
cancer (1 paper, 2022). A tumor composed of atypical neoplastic, often pleomorphic cells that invade other tissues. "In the analysis of key genes co-expression, we found the four genes (CDC73/CDC123/B4GALT1/CUL2) are most relevant to the expression of key genes and also related to the occurrence of many cancers." (PMID 35111402, 2022).
tumor (1 paper, 2025). "An analysis of the relationships between GRSF1 and tumor stem cell markers revealed significant positive associations with UBE2K, XRCC5, SNRPD3, and CDC123 (Appendix B Figure A2c), which was consistent with previous findings." (PMID 40722682, 2025).
CDC123 also shares sentences with these, for which no sentence is quoted: breast carcinoma (1 paper); lipodystrophy (1).